TRIM6 (tripartite motif containing 6)
Description:
E3 ubiquitin ligase that plays a crucial role in the activation of the IKBKE-dependent branch of the type I interferon signaling pathway. In concert with the ubiquitin-conjugating E2 enzyme UBE2K, synthesizes unanchored 'Lys-48'-linked polyubiquitin chains that promote the oligomerization and autophosphorylation of IKBKE leading to stimulation of an antiviral response. Also ubiquitinates MYC and inhibits its transcription activation activity, maintaining the pluripotency of embryonic stem cells (By similarity). Promotes the association of unanchored 'Lys-48'-polyubiquitin chains with DHX16 leading to enhanced RIGI-mediated innate antiviral immune response. (Microbial infection) Ubiquitinates ebolavirus protein VP35 leading to enhanced viral transcriptase activity.
Synonyms: RNF89
Tractability: No criterion of Open Targets' tractability assessment is met for any kind of drug.
Gene: Protein-coding gene on chromosome 11 (5,596,109 to 5,612,958, forward strand). Ensembl gene ENSG00000121236.
Subcellular location: Cytoplasm
Pathways (Reactome):
Immune System: Interferon gamma signaling
Gene Ontology:
Molecular function: identical protein binding; protein binding; protein kinase binding; protein tyrosine kinase binding; protein-macromolecule adaptor activity; ubiquitin protein ligase activity; DNA-binding transcription factor binding; zinc ion binding
Biological process: antiviral innate immune response; cellular response to interferon-beta; free ubiquitin chain polymerization; negative regulation of gene expression; negative regulation of viral genome replication; positive regulation of cytokine production involved in immune response; positive regulation of defense response to virus by host; positive regulation of peptidyl-serine phosphorylation; positive regulation of peptidyl-threonine phosphorylation; positive regulation of transcription regulatory region DNA binding; positive regulation of type I interferon-mediated signaling pathway; protein K48-linked ubiquitination; regulation of non-canonical NF-kappaB signal transduction; response to lipopolysaccharide; innate immune response; regulation of gene expression; cellular response to virus; negative regulation of DNA-templated transcription; negative regulation of stem cell differentiation; positive regulation of gene expression; protein polyubiquitination; protein ubiquitination
Cellular component: cytoplasm; cytosol; nucleus
Genetic constraint (gnomAD): Loss-of-function variants: 38 observed, 48.8 expected, observed/expected ratio (o/e) 0.78, 90% interval 0.6 to 1.02. The upper end of that interval is the gene's LOEUF score, 1.02, which puts it in group 4 of 6, group 1 being the genes least tolerant of losing a copy. Missense variants: 634 observed, 621.35 expected, observed/expected ratio (o/e) 1.02, 90% interval 0.95 to 1.09. Synonymous variants: 205 observed, 235.14 expected, observed/expected ratio (o/e) 0.87, 90% interval 0.78 to 0.98.
Homologues: Orthologues: macaque TRIM6 (96% identical), dog TRIM6 (78% identical), rabbit TRIM6 (77% identical), pig TRIM6 (77% identical), rat Trim6 (77% identical), guinea pig TRIM6 (76% identical), mouse Trim6 (76% identical). Paralogues in human: TRIM22 (54% identical), TRIM34 (53% identical), TRIM5 (53% identical), TRIM68 (36% identical), TRIM21 (35% identical), TRIM38 (34% identical), TRIM60 (28% identical), TRIM58 (28% identical), TRIM27 (28% identical), TRIM39 (28% identical), TRIM11 (26% identical), TRIM61 (26% identical), and 68 more.
Diseases named in the same sentence as TRIM6 in open-access papers:
TRIM6 is named in the same sentence as 34 diseases in open-access papers, as found by Europe PMC text mining. Sharing a sentence is not in itself a finding about the gene and the disease. The quoted sentences say what the papers report.
viral infection (7 papers, 2016 to 2025). "Upon viral infection, IKKε can be activated by the unanchored K48-linked polyubiquitin chain generated by TRIM6, leading to downstream STAT1 activation." (PMID 39823515, 2025). "The functions of TRIM6 in viral infection and inflammatory responses have been identified in earlier investigations." (PMID 37759698, 2023). "Previous research has identified roles for TRIM6 in viral infection and inflammatory responses." (PMID 37759698, 2023). "Interestingly, IFITM1/2/3, and TRIM6, common to all four gene sets, were shown to repress viral infection." (PMID 38201278, 2023). "In addition, the differentially methylated TRIM6 locus associated with SCT is involved in type 1 interferon signaling and the immune response to viral infection and may have implications for susceptibility of individuals with SCT to infectious pathogens." (PMID 40758858, 2025). "TRIM6 and TRIM22 have both been reported to drive innate immune responses to viral infection." (PMID 40216791, 2025).
colorectal cancer (6 papers, 2020 to 2025). A primary or metastatic malignant neoplasm that affects the colon or rectum. "Secondly, knockdown of TRIM6 has been reported to increase the sensitivity to 5-fluorouracil and oxaliplatin in colorectal cancer." (PMID 38813007, 2023). "Through this signaling pathway, TRIM6 can enhance the migration and metastasis of colorectal cancer." (PMID 38813007, 2023). "Tripartite motif 6 (TRIM6) acts as an E3-ubiquitin ligase and can promote the progression of human colorectal cancer." (PMID 36654781, 2023). "Another downstream effector of TRIM6 in colorectal cancer is STAT3 (signal transducer and activator of transcription 3)." (PMID 38813007, 2023). "TRIM6 accelerated the growth and metastasis of breast cancer and colorectal cancer." (PMID 35884544, 2022). "The expression levels of TRIM6 were assessed in colorectal cancer (CRC) samples." (PMID 31992359, 2020).
glioma (5 papers, 2022 to 2025). A benign or malignant brain and spinal cord tumor that arises from glial cells (astrocytes, oligodendrocytes, ependymal cells). "In this study, we demonstrate that TRIM6 expression is significantly upregulated in glioma samples and investigate the association between TRIM6 expression and clinical characteristics of glioma patients." (PMID 37759698, 2023). "We analyzed the mRNA expression levels of TRIM6 in various clinical categories using the TCGA database to explore the association between TRIM6 expression and clinical features in glioma patients." (PMID 37759698, 2023). "Our results show that TRIM6 is predominantly overexpressed in glioma tissues and is associated with reduced overall survival, disease-specific survival, and progression-free interval." (PMID 37759698, 2023). "In summary, TRIM6 is significantly upregulated in gliomas and linked to poor prognosis, making it a potential diagnostic and prognostic biomarker." (PMID 37759698, 2023). "The disease-specific survival (DSS) and progression-free interval (PFI) analyses yielded consistent results with the OS analysis, further indicating that TRIM6 expression is associated with worse survival in Glioma patients." (PMID 37759698, 2023). "In the univariate model, WHO grade, IDH status, 1p/19q codeletion, primary therapy outcome, age, histological type, and TRIM6 expression were all significantly associated with OS in Gliomas (all p < 0.05)." (PMID 37759698, 2023). "According to the TCGA database, TRIM6 expression can be considered a discriminatory factor based on the ROC analysis, with an area under the curve (AUC) of 0.821, indicating its potential as a diagnostic biomarker for Gliomas relative to normal tissue." (PMID 37759698, 2023). "In addition, a high TRIM6 expression in Gliomas is associated with poor OS, DSS, and PFI." (PMID 37759698, 2023). "Our results demonstrated that the expression of TRIM6 was significantly up-regulated in Gliomas samples compared to normal tissues, suggesting that TRIM6 may be a suitable target for the development of diagnostic techniques for patients with Gliomas and may be exploited in therapeutic settings." (PMID 37759698, 2023). "Therefore, it is possible that the already pronounced adverse prognosis associated with Grade 4 gliomas could overshadow any potential association between TRIM6 expression levels and survival." (PMID 37759698, 2023). "Research has shown that in glioma, Tripartite Motif Containing 6 (TRIM6) modulates the interaction between cytokines and their receptors, contributing to inflammatory responses and immune regulation imbalance, thereby influencing glioma progression." (PMID 40656893, 2025). "The Transwell assay provided additional evidence for the involvement of TRIM6 in glioma cell invasion and migration." (PMID 37759698, 2023). "To explain the underlying molecular mechanism by which TRIM6 influences the prognosis of Gliomas, we compared the gene expression profiles between TRIM6 high- and low-expression groups using the TCGA-GBMLGG database." (PMID 37759698, 2023). "The OS study demonstrated that Glioma patients with high TRIM6 expression had a significantly poorer prognosis than those with low TRIM6 expression (p < 0.001)." (PMID 37759698, 2023). "Taking it together, the current study found that TRIM6 expression is significantly upregulated and related to poor prognosis in Glioma patients." (PMID 37759698, 2023). "TRIM6 plays a crucial role in promoting cell viability, clonogenic potential, migration, and invasion in glioma cells." (PMID 37759698, 2023). "Consistent with our findings, bioinformatics data revealed that glioma patients with higher TRIM6 level experience worse prognoses." (PMID 38813007, 2023). "We explored the correlation between the expression of TRIM6 and the level of immune infiltration of Gliomas." (PMID 37759698, 2023).
glioma (continued). "In contrast, the infiltration of CD8 T cells, NK CD56bright cells, pDC, Tcm, TFH, and Tgd was significantly lower in Glioma patients with high TRIM6 expression compared to those with low TRIM6 expression." (PMID 37759698, 2023). "The results demonstrated significantly higher TRIM6 expression in Glioma tissue compared to normal tissues." (PMID 37759698, 2023). "In vitro experiments demonstrate that silencing TRIM6 impairs the proliferation, invasion, and migration of glioma cells, while overexpressing TRIM6 enhances these abilities." (PMID 37759698, 2023). "The cell wound healing assay and Transwell assay were performed to assess the impact of TRIM6 on the invasive and migratory abilities of glioma cells." (PMID 37759698, 2023). "To investigate the potential role of TRIM6 in the development of Gliomas, we compared the gene expression profiles of TRIM6 high-expression (n = 351) and low-expression (n = 350) groups using RNAseq." (PMID 37759698, 2023). "Our findings from the CCK8 assay demonstrated that the knockdown of TRIM6 in U251 glioma cells resulted in a significant decrease in cell viability compared to the control group." (PMID 37759698, 2023). "TRIM6 plays a significant role in promoting cell viability, clonogenic potential, migration, and invasion in glioma cells." (PMID 37759698, 2023). "To better understand the role of the TRIM6 gene in gliomas, we analyzed the correlation between TRIM6 expression and patient prognosis using data from The Cancer Genome Atlas (TCGA)." (PMID 37759698, 2023). "The analysis revealed a significant increase in TRIM6 transcription levels in Gliomas compared to normal adjacent tissues, as evident from both GSE109569 (p < 0.05) and GSE76070 datasets (p < 0.001)." (PMID 37759698, 2023). "This study investigates the expression and prognostic value of TRIM6 in gliomas, the most prevalent primary brain and spinal cord tumors." (PMID 37759698, 2023). "We employed univariate and multivariate analysis to determine the impact of TRIM6 expression on Glioma patients." (PMID 37759698, 2023). "We initially assessed the expression levels of TRIM6 in two glioma cell lines, U251 and U373, using qPCR analysis." (PMID 37759698, 2023). "In the multivariate analyses, TRIM6, as well as WHO grade, IDH status, primary therapy outcome, gender, and age, remained significantly associated with OS in Gliomas (HR = 1.591, 95% CI = 1.027–2.466, p = 0.038)." (PMID 37759698, 2023). "Moreover, the expression of TRIM6 in Gliomas was related with advanced clinicopathological features, according to our findings (WHO grade, Histological type, age sex and Primary therapy outcome)." (PMID 37759698, 2023). "For the diagnosis and prognosis of gliomas, TRIM6 has certain reference values." (PMID 37759698, 2023). "In this study, we observed abnormal high expression of TRIM6 in Gliomas, which led us to speculate that TRIM6 might be involved in regulating the tumor immune response." (PMID 37759698, 2023). "Firstly, despite concluding that TRIM6 expression is strongly associated with Cytokine-cytokine receptor interaction, immune infiltration and Gliomas’ prognosis, we lack direct evidence that TRIM6 influences prognosis through Cytokine-cytokine receptor interaction or immune infiltration." (PMID 37759698, 2023). "TRIM6 may regulate the progression of Gliomas by regulating the Cytokine-cytokine receptor interaction, thus enhances the inflammatory response, affecting immunomodulation imbalance." (PMID 37759698, 2023). "Furthermore, we validated the expression of TRIM6 and 9 key genes closely related to TRIM6 in gliomas using RT-qPCR experiments." (PMID 37759698, 2023). "Our findings suggest that TRIM6 may serve as a biomarker for predicting the prognosis and immune infiltration of individuals with gliomas." (PMID 37759698, 2023).
glioma (continued). "Moreover, we experimentally confirmed in vitro that knockdown of TRIM6 can inhibit the proliferation, invasion, and migration abilities of glioma cells, while overexpression of TRIM6 can enhance these abilities." (PMID 37759698, 2023). "To further validate the expression level of TRIM6 in Gliomas, we utilized two additional independent external GEO datasets (validation cohort), namely GSE109569 and GSE76070, to analyze TRIM6 transcription levels in cancer tissues and adjacent tissues of Gliomas." (PMID 37759698, 2023). "To corroborate the protein expression level of TRIM6 in Gliomas, we examined the HPA database, which confirmed higher TRIM6 expression levels in glioma tumor tissues compared to healthy cerebral cortex tissues." (PMID 37759698, 2023). "The AUC for TRIM6 expression in Glioblastoma (GBM) and Lower Grade Glioma (LGG) is 0.961 and 0.791, respectively." (PMID 37759698, 2023). "The results further supported our observations, showing a significant upregulation of TRIM6 mRNA expression levels in the glioma tumor tissues when compared to the adjacent non-tumor tissues." (PMID 37759698, 2023).
renal fibrosis (5 papers, 2020 to 2025). A final common manifestation of a wide variety of chronic kidney diseases characterized by glomerulosclerosis and tubulointerstitial fibrosis. "In this study, we have reported that TRIM6 is tightly associated with renal fibrosis by participating in the regulation of the mTORC1 signaling." (PMID 33634104, 2020). "In our research, we found that TRIM6 expression was positively correlated with the severity of renal fibrosis." (PMID 33634104, 2020). "Considering that ROS can activate the NF- κB signaling, we queried the GSEA and found that the expression of TRIM6 in renal fibrosis was tightly correlated with the NF-κB signaling." (PMID 33634104, 2020). "Collectively, these results indicate that knockdown of TRIM6 can alleviate renal fibrosis in 5/6 NX rats." (PMID 33634104, 2020). "Using quantitative RT-PCR, we then explored the TRIM6 transcription level in the tissues obtained from 75 cases of renal fibrosis." (PMID 33634104, 2020). "More importantly, the suppressed expression of TRIM6 by shRNAs largely attenuated renal fibrosis in vitro and in vivo, suggesting that TRIM6 can be used as a potential therapeutic target for renal fibrosis." (PMID 33634104, 2020). "Our work blazes a new way for a potential therapeutic solution for treating renal fibrosis using TRIM6 inhibitors." (PMID 33634104, 2020). "Our study has uncovered a TRIM6-involved regulatory mechanism of renal fibrosis through the mTOCR1 signaling pathway for the first time." (PMID 33634104, 2020). "With the severity of renal fibrosis score, the protein levels of TRIM6 and the nuclear translocation of p50 increased significantly, while the protein levels of TSC1 and TSC2 decreased significantly in the kidney tissues of the patients." (PMID 33634104, 2020). "Considering the expression of TRIM6 is critical to renal fibrosis, we then investigated how TRIM6 expression is regulated in HK2 cells." (PMID 33634104, 2020). "The revelation of the important regulatory role of ROS and the NF-κB pathway in TRIM6 expression in our study contributes to a better understanding of the entire picture of TRIM6-related signaling pathways in renal fibrosis." (PMID 33634104, 2020). "The expression of TRIM6 was proportional to the severity of renal fibrosis based on the estimated IF/TA score—TRIM6 mRNA expression in the IF/TA 3 group was ~4 times its expression in the IF/TA 0 group." (PMID 33634104, 2020). "Several genes located within or adjacent to SCT-associated differentially methylated regions are related to antioxidant pathways, ROS detoxification, or response to hypoxia or oxidative stress, including TRIM6, which participates in progression of renal fibrosis." (PMID 40758858, 2025). "Snail1 and Twist1, two markers of EMT, and MMP2, a marker of invasion and migration, which could degrade the extracellular matrix, were downregulated in TRIM6 knockdown CRC cells, which is consistent with a study on TRIM6 in renal fibrosis." (PMID 34589421, 2021). "To elucidate the regulatory function of TRIM6 in renal fibrosis, we treated HK2 proximal tubule epithelial cells with Angiotensin II (Ang II), which induces EMT and ER stress during the progression of chronic kidney damage, eventually contributing to renal fibrosis." (PMID 33634104, 2020). "As a result, we have presented the first study on the role of TRIM6 in the mTORC1 pathway in renal fibrosis models and our findings suggested that TRIM6 may be a potential target for the treatment of renal fibrosis." (PMID 33634104, 2020). "Therefore, we used the 5/6 NX rat as an in vivo model to study the effect of TRIM6 knockdown on renal fibrosis." (PMID 33634104, 2020). "We first examined the gene expression pattern of TRIM6 in renal fibrosis tissues." (PMID 33634104, 2020). "Moreover, the knockdown of TRIM6 was found efficient for alleviating renal fibrosis and inhibiting the downstream processes of EMT and ER in both HK2 cells and 5/6-nephrectomized rats." (PMID 33634104, 2020).